EIF3F (eukaryotic translation initiation factor 3 subunit F)
Description:
Component of the eukaryotic translation initiation factor 3 (eIF-3) complex, which is required for several steps in the initiation of protein synthesis. The eIF-3 complex associates with the 40S ribosome and facilitates the recruitment of eIF-1, eIF-1A, eIF-2:GTP:methionyl-tRNAi and eIF-5 to form the 43S pre-initiation complex (43S PIC). The eIF-3 complex stimulates mRNA recruitment to the 43S PIC and scanning of the mRNA for AUG recognition. The eIF-3 complex is also required for disassembly and recycling of post-termination ribosomal complexes and subsequently prevents premature joining of the 40S and 60S ribosomal subunits prior to initiation. The eIF-3 complex specifically targets and initiates translation of a subset of mRNAs involved in cell proliferation, including cell cycling, differentiation and apoptosis, and uses different modes of RNA stem-loop binding to exert either translational activation or repression. Deubiquitinates activated NOTCH1, promoting its nuclear import, thereby acting as a positive regulator of Notch signaling.
Synonyms: EIF3S5; eIF3-epsilon; eIF3-p47; MRT67
Tractability: Small molecule: a structure with a bound ligand is known. PROTAC: ubiquitination databases record sites on it; its protein half-life has been measured.
Target class: Enzyme
Gene: Protein-coding gene on chromosome 11 (7,970,251 to 8,001,862, forward strand). Ensembl gene ENSG00000175390.
Subcellular location: Cytoplasm
Pathways (Reactome):
Metabolism of proteins: Formation of a pool of free 40S subunits; Formation of the ternary complex, and subsequently, the 43S complex; GTP hydrolysis and joining of the 60S ribosomal subunit; L13a-mediated translational silencing of Ceruloplasmin expression; Ribosomal scanning and start codon recognition; Translation initiation complex formation
Gene Ontology:
Molecular function: identical protein binding; metal-dependent deubiquitinase activity; protein binding; translation initiation factor activity; translation initiation factor binding; cysteine-type deubiquitinase activity; deubiquitinase activity; metallopeptidase activity; peptidase activity
Biological process: IRES-dependent viral translational initiation; translational initiation; formation of cytoplasmic translation initiation complex; cytoplasmic translational initiation
Cellular component: eukaryotic translation initiation factor 3 complex; membrane; cytosol; eukaryotic translation initiation factor 3 complex, eIF3m; cytoplasm; eukaryotic 43S preinitiation complex; eukaryotic 48S preinitiation complex; synapse
Genetic constraint (gnomAD): Loss-of-function variants: 8 observed, 31.36 expected, observed/expected ratio (o/e) 0.26, 90% interval 0.15 to 0.46. The upper end of that interval is the gene's LOEUF score, 0.46, which puts it in group 2 of 6, group 1 being the genes least tolerant of losing a copy. Missense variants: 418 observed, 433.57 expected, observed/expected ratio (o/e) 0.96, 90% interval 0.89 to 1.04. Synonymous variants: 178 observed, 167.68 expected, observed/expected ratio (o/e) 1.06, 90% interval 0.94 to 1.2.
Gene-disease validity (ClinGen):
ClinGen rates the evidence that EIF3F causes each of these diseases.
syndromic intellectual disability (autosomal recessive): Definitive. A intellectual disability that is part of a larger syndrome.
Homologues: Orthologues: macaque EIF3F (97% identical), rabbit EIF3F (95% identical), dog EIF3F (94% identical), mouse Eif3f (92% identical), rat Eif3f (92% identical), pig EIF3F (88% identical), guinea pig EIF3F (85% identical), tropical clawed frog eif3f (61% identical), zebrafish eif3f (61% identical), Drosophila melanogaster eIF3f1 (38% identical), Caenorhabditis elegans eif-3.F (29% identical), Drosophila melanogaster eIF3f2 (29% identical). Paralogues in human: PSMD7 (22% identical), COPS6 (20% identical).
Diseases named in the same sentence as EIF3F in open-access papers:
EIF3F is named in the same sentence as 51 diseases in open-access papers, as found by Europe PMC text mining. Sharing a sentence is not in itself a finding about the gene and the disease. The quoted sentences say what the papers report.
pancreatic cancer (13 papers, 2010 to 2025). "In melanoma and pancreatic cancer, eIF3f was down-regulated, and the overexpression of eIF3f was noted to be associated with an inhibition of proliferation and an increased apoptosis in both pancreatic cancer and melanoma cell lines." (PMID 32498447, 2020). "Using loss of heterozygosity and gene copy number analyses, it has been demonstrated that there is an allelic loss of eIF3f gene in human melanoma and in pancreatic cancer cells." (PMID 23354061, 2013). "However, loss of the eIF3f gene has been observed in melanoma and pancreatic cancer, which results in the downregulation of eIF3f." (PMID 26988917, 2016). "Loss of eIF3f in pancreatic cancer may contribute to tumor cells' evading apoptosis via upregulation of protein synthesis." (PMID 22457825, 2012). "Reduction of eIF3f expression was also reported in melanocytic neoplasms, pancreatic cancers, breast and ovary cancers, and eIF3f together with eIF3e were the only members of the eIF3 complex found to be reduced in these cancers." (PMID 41423661, 2025). "In fact, decreased eIF3f mRNA transcript levels are commonly detected in tumors such as breast cancer, ovarian cancer, melanoma, and pancreatic cancer." (PMID 36360287, 2022). "On the other hand, other subunits like eIF3F have been reported to be down-regulated in breast cancer, vulvar cancer, pancreatic cancer, and ovarian cancer among others." (PMID 36015341, 2022). "eIF3f is the only central component of eIF3 complex which has been found to be down-regulated in melanoma and pancreatic cancer." (PMID 33148274, 2020). "Endogenous levels of both eIF3f mRNA and protein levels are reduced in pancreatic cancer cells, whereas eIF3f-overexpressing NIH3T3 cells have shown reduced cell proliferation and induced apoptosis." (PMID 28083147, 2016). "Increased expression of eIF3f reduces cellular growth by inducing apoptosis in melanoma and pancreatic cancer cells." (PMID 26988917, 2016). "Previous studies have demonstrated that overexpression of eIF3f inhibits cell proliferation and induces apoptosis in melanoma and pancreatic cancer cells, suggesting that downregulation of eIF3f is involved in tumorigenesis for many types of cancer." (PMID 24678890, 2014). "Two other eIF3 subunits, eIF3e and eIF3f, are downregulated in human breast/lung carcinomas and melanoma/pancreatic cancer, respectively." (PMID 23354061, 2013). "Enforced expression of eIF3f inhibits translation, cellular growth and proliferation, and induces apoptosis in melanoma and pancreatic cancer cells." (PMID 23354061, 2013). "We previously reported decreased eukaryotic initiation factor 3 subunit f (eIF3f) expression in pancreatic cancer." (PMID 22457825, 2012). "MiaPaCa-2 pancreatic cancer cell line has a decreased eIF3f expression, therefore was used in the following eIF3f-restoration experiments." (PMID 22457825, 2012). "In our study, quantification of the rRNA level by real time RT-PCR showed that 28S and 18S rRNA decreased up to 70% in eIF3f-restored MiaPaCa-2 pancreatic cancer cells." (PMID 22457825, 2012). "We found that restoration of eIF3f expression in pancreatic cancer cells led to decreased rRNA, especially 28S rRNA." (PMID 22457825, 2012). "eIF3f overexpression hasbeen associated with inhibition of HIV-1 replication and with activation ofapoptosis in melanoma and pancreatic cancer cells." (PMID 20126553, 2010). "eIF3f is the only eIF3 subunit that is downregulated in pancreatic cancer and melanoma." (PMID 36360287, 2022). "Indeed, the reduced transcription levels of eIF3f mRNA are usually detected in tumors including breast cancer, pancreatic cancer, ovarian cancer and melanomas." (PMID 33148274, 2020).
pancreatic cancer (continued). "Moreover, increased eIF3f inhibits translation and cell growth and induces apoptosis in melanoma and pancreatic cancer cells." (PMID 26988917, 2016). "Our findings support the tumor suppressive role of eIF3f in pancreatic cancer." (PMID 22457825, 2012). "Our study demonstrated an unexpected function of a human translation initiation factor in rRNA degradation, linking translation initiation to the rRNA degradation mechanism and shedding light on the molecular mechanisms of the tumorigenic role of eIF3f in pancreatic cancer." (PMID 22457825, 2012). "Restoration of eIF3f expression in BxPC3 and MiaPaCa-2 pancreatic cancer cells induced apoptosis." (PMID 22457825, 2012). "Enforced overexpression of eIF3f inhibits protein synthesis and cell proliferation, and induced apoptosis in melanoma and pancreatic cancer, whereas knocking down the expression of eIF3f protects melanoma cells from apoptosis, indicating eIF3f may function as a negative regulator for translation." (PMID 33148274, 2020). "eIF3f induces apoptosis by inhibiting protein synthesis and proliferation in pancreatic cancer and melanoma cells, whereas eIF3f may act as a negative regulator of translational effects, and its low expression protects melanoma cells from apoptosis." (PMID 36360287, 2022). "Unlike eIF3e, eIF3f is consistently shown to function as a tumor suppressor in pancreatic cancer." (PMID 28083147, 2016).
melanoma (12 papers, 2010 to 2023). A malignant, usually aggressive tumor composed of atypical, neoplastic melanocytes. "The discovery that eIF3f can interact with the heterogenous nuclear ribonucleoprotein K (hnRNP K) during apoptosis in melanoma and HPDE cells corroborates this model." (PMID 23354061, 2013). "Yeast two-hybrid screens have indicated that the most abundant Mss4 interaction partner is eIF3f, and studies on A7 melanoma cells have shown that Mss4 neutralizes the translation inhibitory effect of eIF3f." (PMID 23354061, 2013). "In particular, 100 % of pancreas and vulva tumors, 90 % of breast tumors, 71 % of melanomas, and 70 % of ovary and small intestine tumors showed a significant decrease of eIF3f expression." (PMID 23354061, 2013). "Knockdown of endogenous eIF3f by siRNA attenuates apoptosis in melanoma cells after treatment with staurosporine as apoptotic agent." (PMID 23354061, 2013). "After anti-Fas or staurosporine treatments in human melanoma cells, the caspase-processed C-terminal fragment CDK11p46 strongly interacts with eIF3f via its Mov34 domain and, due to its kinase activity, phosphorylates eIF3f inducing the inhibition of translation." (PMID 23354061, 2013). "However, confocal microscopy images of human melanoma cells show that eIF3f is localized at both cytoplasmic and nuclear levels." (PMID 23354061, 2013). "EIF3F lacks expression in melanoma, unlike in benign pathological change of skin, such as mole." (PMID 22734884, 2012).
glioma (4 papers, 2013 to 2023). A benign or malignant brain and spinal cord tumor that arises from glial cells (astrocytes, oligodendrocytes, ependymal cells). "In both the CGGA and TCGA datasets, the expression levels of eIF3d, eIF3e, eIF3f, eIF3h and eIF3l highly were associated with the IDH mutant status of gliomas." (PMID 31171919, 2019).
ovarian cancer (3 papers, 2016 to 2025). A primary or metastatic malignant neoplasm involving the ovary. "Similarly, several previous studies reported that eIF3f expression was reduced in cervical and ovarian cancer by ~60-70%." (PMID 26988917, 2016).
autism (2 papers, 2024 to 2025). Persistent deficits in social interaction and communication and interaction as well as a markedly restricted repertoire of activity and interest as well as repetitive patterns of behavior. "A total of 46% of these variants were previously reported in patients with several clinical conditions according to the ClinVar database; only one of them, particularly variant chr11-7994466T > G in EIF3F, was reported in a patient with autism." (PMID 40869941, 2025).
autosomal-recessive intellectual developmental disorder 67 (2 papers, 2024 to 2025). "In particular, intellectual developmental disorder autosomal recessive 67 is caused by a homozygous mutation in the EIF3F gene located in the 11p15.4 region." (PMID 39723281, 2024). "In humans, a different gene coding for a subunit in the eIF3 complex, EIF3F (MIM: 603914), is associated with autosomal-recessive intellectual developmental disorder 67 (MIM: 618295)." (PMID 41033306, 2025).
breast carcinoma (2 papers, 2022). "According to the database, we discovered a lower expression of EIF3E and EIF3F in breast cancer." (PMID 35040374, 2022).
cervical cancer (2 papers, 2016 to 2023). A primary or metastatic malignant neoplasm involving the cervix. "eIF3f injected into a xenograft model of human cervical cancer in nude mice markedly inhibited tumor growth." (PMID 26988917, 2016). "Exponentially growing HeLa cervical cancer cells were transfected transiently with eIF3f expression or control vector, and the cells were injected subcutaneously into immune-deficient BALB/c nude mice." (PMID 26988917, 2016).
colorectal cancer (2 papers, 2023 to 2025). A primary or metastatic malignant neoplasm that affects the colon or rectum. "Eukaryotic Initiation translation factor 3, f subunit (eIF3f) is involved in critical biological functions; however, its role independent of protein translation in regulating colorectal cancer (CRC) is not characterized." (PMID 37544925, 2023).
developmental delay (2 papers, 2024 to 2025). "This EIF3F-related syndrome is characterized by intellectual disability, developmental delay, behavioral abnormalities, hypertonia and/or hypotonia, hearing loss, and short stature." (PMID 41033306, 2025).
epilepsy (2 papers, 2021 to 2022). A brain disorder characterized by episodes of abnormally increased neuronal discharge resulting in transient episodes of sensory or motor neurological dysfunction, or psychic dysfunction. "Mutations of the EIF3F gene were associated with recessive developmental disorders characterized by ID, epilepsy, behavioral problems, and various physical abnormalities." (PMID 35743796, 2022).
gastric cancer (2 papers, 2014 to 2019). A primary or metastatic malignant neoplasm involving the stomach. "eIF3f expression is significantly decreased in many human cancers, and the decreased expression of eIF3f is a significant factor for a poor prognosis for gastric cancer patients." (PMID 31423012, 2019). "However, the expression of eIF3f in gastric cancer (GC) is not well understood to date." (PMID 24678890, 2014).
lung adenocarcinoma (2 papers, 2010 to 2020). A carcinoma that arises from the lung and is characterized by the presence of malignant glandular epithelial cells. "Here, the noncanonical function of EIF3F was studied in human lung adenocarcinoma by combining methods that revealed both the protein–protein and the protein–DNA interactions of this factor." (PMID 31527668, 2020). "The distribution of EIF3F expression in lung adenocarcinoma (LUAD) remains unclear and large-cohort analyses, as proposed by The Cancer Genome Atlas (Genomic Data Common (GDC)-TCGA), are required to study the distribution of EIF3F expression in the disease." (PMID 31527668, 2020).
lung carcinoma (2 papers, 2020 to 2025). "Lastly, we demonstrate that targeting STAT3 in EIF3F-overexpressing human lung cancer cells inhibits cell invasion." (PMID 31527668, 2020). "In our study, we observed that ectopic overexpression of EIF3F in human lung cancer cells alters cell proliferation and bioenergetics but also promotes metastasis in vivo." (PMID 31527668, 2020). "For instance, we found that EIF3F cooperates with STAT3 and exploited this finding to successfully target EIF3F-overexpressing human lung cancer cells with nifuroxazide, an FDA-approved oral anti-diarrheal agent that has been identified as an inhibitor of STAT3." (PMID 31527668, 2020). "We verified the effect of EIF3F overexpression on metastasis in two additional orthotopic mouse models of LUAD generated with H460 and H1975 human lung cancer cells." (PMID 31527668, 2020).
pancreatic adenocarcinoma (2 papers, 2012 to 2023). "Using quantum dot (Qdot)-labeled eIF3f antibody, we demonstrated that eIF3f was markedly decreased in pancreatic adenocarcinoma tissue, as compared with normal pancreatic ducts." (PMID 22457825, 2012).
Atrophy (1 paper, 2010). Any weakening or degeneration, especially through lack of use. "Interestingly, the Mov34 motif in eIF3f interacts directly with theLeucine Charged Domain (LCD) of MAFbx during atrophy." (PMID 20126553, 2010). "In the present work, we show in MAFbx-induced atrophy that the decreased activity ofmTORC1 is correlated with the degradation of eIF3f and inversely mTOR and itsdownstream targets S6K1 and 4E-BP1 via eIF3f control muscle size." (PMID 20126553, 2010). "Here we present evidence that in MAFbx-induced atrophy thedegradation of eIF3f suppresses S6K1 activation by mTOR, whereas an eIF3f mutantinsensitive to MAFbx polyubiquitination maintained persistent phosphorylation ofS6K1 and rpS6." (PMID 20126553, 2010).
Cachexia (1 paper, 2013). Severe weight loss, wasting of muscle, loss of appetite, and general debility related to a chronic disease. "Thus, eIF3f represents a lead candidate to use for biotherapeutic applications for both inhibiting the growth of cancer cells or muscle atrophy and, thus, preventing its progression into irreversible cachexia." (PMID 23354061, 2013).
coloboma (1 paper, 2025). An abnormality in which a part of a structure in one or both eyes is missing. "Structural defects such as TOF, cleft lip and palate, and coloboma have also been observed in individuals with EIF3F-related disorder." (PMID 41033306, 2025).
glioblastoma (1 paper, 2026). The most malignant astrocytic tumor (WHO grade IV). "Depletion of PDCD4 in glioblastoma (GBM) cells resulted in decreased levels of certain eIF3 subunits, including eIF3F." (PMID 42123540, 2026).
leukodystrophy (1 paper, 2024). Leukodystrophies are a group of rare, progressive, metabolic, genetic diseases that affect the brain, spinal cord and often the peripheral nerves. "Another case study engaging MRI revealed extensive supratentorial leukodystrophy; however, the patient was a compound heterozygote in EIF3F." (PMID 39723281, 2024).
myopia (1 paper, 2021). "In regard to this study’s ophthalmologic findings, some of these (hyper-/ myopia) might not necessarily be related to EIF3F deficiency, as they are common in the general population." (PMID 33736665, 2021).
ovarian clear cell cancer (1 paper, 2020). An invasive malignant neoplasm that arises from the ovary and is characterized by a predominance of clear and hobnail malignant epithelial cells. "All of the genes were upregulated compared with normal ovarian tissue, except for eIF3f, which exhibited down-regulation in the tissue of ovarian clear cell carcinoma." (PMID 32498447, 2020).
prostate carcinoma (1 paper, 2026). A carcinoma that arises from epithelial cells of the prostate gland. "This study reveals that CCT2 promotes lipid metabolic reprogramming and tumor progression in prostate cancer by cooperating with EIF3F to stabilize FASN, highlighting the CCT2-EIF3F-FASN axis as a potential target for metabolic intervention." (PMID 42231807, 2026).
prostate tumours (1 paper, 2015). "Several other genes at this locus, including CYB5R2, EIF3F, NLRP10, OLFML1 and OVCH2, were also found to be significantly expressed in prostate tumours in comparison with normal tissues." (PMID 26443449, 2015).